DDB1 (damage specific DNA binding protein 1)
Diseases named in the same sentence as DDB1 in open-access papers (continued):
Sharing a sentence is not in itself a finding about the gene and the disease.
ovarian carcinoma (5 papers, 2017 to 2025). A malignant neoplasm originating from the surface ovarian epithelium. "Mitochondrial dysregulation is closely related to diseases such as ovarian cancer, CRL4CUL4 A/DDB1 regulates chemotherapy resistance in ovarian cancer cells by modulating mitochondrial dynamics and autophagy." (PMID 40438494, 2025). "In detail, DDB1 is part of the CRL4 complex which in cisplatin-resistant ovarian cancer seems to be considerably overactivated." (PMID 37024667, 2023). "In an effort to further understand the biological role of CRL4 in cisplatin resistance of ovarian cancer, we first knocked down Cul4A and DDB1, respectively, with shRNAs and examined cell viability in response to cisplatin treatment." (PMID 30718461, 2019). "To identify whether CRL4 is also involved in cisplatin resistance, we examined the expression levels of Cul4A and DDB1 in cisplatin-sensitive ovarian cancer cell A2780 and cisplatin-resistant cell A2780CP by western blot and QRT-RCR." (PMID 30718461, 2019). "To identify the roles of CUL4-DDB1 E3 ligase complex in ovarian cancer cells, we performed a knockdown of CUL4-DDB1 E3 ligase components, ring of cullin-1 (ROC1), DDB1, or DDB1/CUL4-associated factor-1 (DCAF1) in A2780 cells, and detected 5hmC levels by dot-blot assays." (PMID 29156803, 2017). "To detect the expression of CRL4 in ovarian cancer, we examined the levels of CRL4 (Cul4A and DDB1) E3 ligase in ovarian cancer tissues and normal interstitial tissues." (PMID 30718461, 2019). "Furthermore, a recent study suggested that DDB1 and Cullin-RING ubiquitin ligases (CRL) 4, the ubiquitin ligase of Cullin 4A (CUL4A)-DDB1 E3, are important factors in ovarian cancer chemoresistance because they regulate apoptosis and might be therapeutic targets for patients after cisplatin failure." (PMID 31842285, 2019). "Interestingly, we found that both Cul4A and DDB1 expression levels were increased in A2780CP compared with that in A2780, suggesting CRL4 may play a key role in triggering cisplatin resistance of ovarian cancer." (PMID 30718461, 2019).
HIV-1 infection (4 papers, 2008 to 2020). The type species of lentivirus and the etiologic agent of acquired immunodeficiency syndrome (AIDS). "While packaging of Vpx in HIV-1 particles markedly increased infectivity for macrophages transfected with a scrambled siRNA silencing of DDB1 in macrophages significantly reduced (p<0.002) the ability of Vpx to enhance HIV-1 infection." (PMID 18451984, 2008). "Our study also indicates that DDB1 is required for the ability of Vpx to counter the macrophage restriction to HIV-1 infection." (PMID 18451984, 2008). "The biochemical mechanisms mediating Vpr function in HIV-1 infection are mainly related to Vpr ability to usurp the Cul4-DDB1[VprBP] E3 ubiquitin ligase complex comprising the Cullin 4 (Cul4) scaffold, DDB1 linker protein, DDA1 core subunit, and DCAF1 substrate receptor, to which Vpr binds." (PMID 32778120, 2020). "We next examined whether DDB1 was required for the ability of Vpx to counteract the restriction to HIV-1 infection." (PMID 18451984, 2008). "For this reason, silencing of DDB1 did not impair susceptibility of macrophages to HIV-1 infection." (PMID 18451984, 2008). "Therefore, we examined whether the ability of Vpx to counteract the macrophage restriction to SIV and HIV-1 infection was DDB1-dependent." (PMID 18451984, 2008). "Similar to the results obtained with siRNA mediated DDB1 depletion, depletion of DDB1 using DDB1-specific shRNAs also specifically impaired the susceptibility of primary macrophages to SIV infection but not HIV-1 infection." (PMID 18451984, 2008).
liver cancer (4 papers, 2012 to 2024). An epithelial or non-epithelial malignant neoplasm that arises from the liver. "The authors noted that the oncogenic poly(ADP-ribose) glycohydrolase (PARG) influences DDB1 stability, and suggested a role for the PARG–DDB1 interplay in HBV infection and liver cancer development." (PMID 38757942, 2024). "The DDB1 mutant mice can be broadly applied to studies of HSC differentiation, HSC niche and HSCs as origin of liver cancer." (PMID 22384083, 2012).
xeroderma pigmentosum (4 papers, 2007 to 2024). Xeroderma pigmentosum (XP) is a rare genodermatosis characterized by extreme sensitivity to ultraviolet (UV)-induced changes in the skin and eyes, and multiple skin cancers. "The significance of arginine 273 in the WDXR submotif in DDB2 is underscored by its mutation to histidine (R273H) in a xeroderma pigmentosum (XP) group E patient and its failure to bind to DDB1." (PMID 17280619, 2007). "On the other hand, DNA damage‐binding 1 (DDB1) and DDB2 are recruited in the non-transcribed region to be detected by xeroderma pigmentosum (XP) group E (XPE) in a TCR manner." (PMID 38630271, 2024).
Cockayne syndrome A (3 papers, 2013 to 2021). "Interestingly, many protein-containing “WDxR” motifs in their WD40 repeat regions enhance the repair of damaged DNAs as seen in Cockayne syndrome A (CSA), damaged DNA binding protein 1 (DDB1), and WRAP53 beta." (PMID 34210031, 2021).
colorectal cancer (3 papers, 2020 to 2025). A primary or metastatic malignant neoplasm that affects the colon or rectum. "Ultimately, DDB1-mediated PHGDH mono-ubiquitination drives colorectal cancer metastasis." (PMID 40598535, 2025). "DDB1 increases poly-ubiquitination and degradation of PHGDH, inhibiting colorectal cancer growth and stemness via an enzyme-independent mechanism." (PMID 40598535, 2025).
Obesity (3 papers, 2024 to 2026). Accumulation of substantial excess body fat. "DDB1 is involved in regulating adipose tissue development and physiological processes related to obesity." (PMID 39199873, 2024). "In our study, DPR attenuates obesity‐induced cardiac remodeling during aging, as evidenced by the normalization of heart weight and the suppression of hypertrophic markers, including Cyclin D1, NPPA, and DDB1." (PMID 41549510, 2026).
pancreatic cancer (3 papers, 2021 to 2025). "Similarly, diminished expression of DDB1 in pancreatic cancer is linked to improved patient survival, and high levels of COPS2 have been shown to predict the occurrence of gastric cancer." (PMID 40524221, 2025). "Recently, a high expression of DDB1 was identified as a poor prognostic factor in pancreatic cancer." (PMID 34207079, 2021).
viral infection (3 papers, 2021 to 2025). "Together these data suggested that loss of Ddb1 in activated CD4+ T cells led to accumulation of DNA damage during acute viral infection." (PMID 34526995, 2021). "Here, we show that Ddb1 is essential for expansion of TFH and Th1 cells, GC response, and antiviral antibody response during acute viral infection." (PMID 34526995, 2021). "Here, we showed that deletion of Ddb1 in effector CD4+ T cells led to impaired TFH and Th1 cell generation due to defect of T-cell expansion upon acute viral infection." (PMID 34526995, 2021). "Here, we reported that Damage-specific DNA binding protein 1 (Ddb1) was required for expansion of CD4+ helper T cells including TFH and Th1 cells, germinal center response, and antibody response to acute viral infection." (PMID 34526995, 2021). "Interestingly, HBx binds with DDB1 at its larger pocket enclosed by its BPA-BPC double propeller fold, using a three-turn α-helix (termed H-box), which is essential for its reported stimulatory activities in cultured cells and might be required for efficient viral infection." (PMID 35956950, 2022).
breast carcinoma (2 papers, 2023). "Analysis of online datasets further revealed augmented PRMT6, PARP1, CUL4B, and DDB1 levels in breast cancer tissues compared with normal tissues." (PMID 36941223, 2023). "The published datasets were analyzed to better understand the association between PRMT6, PARP1, DDB1, and PER3 in breast cancer." (PMID 36941223, 2023).
colon carcinoma (2 papers, 2017 to 2018). "Our recent studies demonstrated a DNA damage-independent interaction between DDB1/DDB2 and XRCC5/XRCC6 in colon cancer cells." (PMID 30410671, 2018).
diabetes (2 papers, 2022 to 2025). "Previous studies found that DDB1-mediated degradation of Cry1 was an important target for insulin action on glucose homeostasis, and the FUT8 was strongly associated with increased susceptibility to diabetes." (PMID 36360309, 2022).
glioma (2 papers, 2017 to 2020). A benign or malignant brain and spinal cord tumor that arises from glial cells (astrocytes, oligodendrocytes, ependymal cells). "In conclusion, gene amplifications specifically gene amplifications of DDB1, EGFR, MDM4 and GFAP can provide information about the cell types and the degree of heterogeneity at the origin of glioma stem-like cells." (PMID 28415661, 2017).
Hepatic steatosis (2 papers, 2021 to 2025). Steatosis is a term used to denote lipid accumulation within hepatocytes. "PPDPF has been reported to inhibit hepatic steatosis by suppressing mTORC1 activity by disrupting the Raptor-DDB1 interaction." (PMID 40582769, 2025). "In conclusion, the current study provides the first evidence that PPDPF inhibits hepatic steatosis via suppression of mTORC1 activity by interfering with Raptor–DDB1 interaction." (PMID 34031390, 2021).
lung adenocarcinoma (2 papers, 2017 to 2025). A carcinoma that arises from the lung and is characterized by the presence of malignant glandular epithelial cells. "The potential biomarker, NKX2-1, binds DNA damage-binding protein 1 (DDB1) and degrades check-point kinase 1 (CHK1) to facilitate lung adenocarcinoma progression." (PMID 29069744, 2017).
meningioma (2 papers, 2020 to 2024). A generally slow growing tumor attached to the dura mater. "We used meningioma tissue and primary cells derived from meningioma tumours to investigate the expression of DDB1 and Cullin 4-associated factor 1 (DCAF1) and KSR1, and confirmed these proteins were overexpressed." (PMID 32629964, 2020).
ovarian tumor (2 papers, 2019 to 2022). "We also used an intraperitoneal tumor xenograft model to further validate the important roles of CRL4CUL4A/DDB1 and mitophagy in ovarian tumor progression." (PMID 36481655, 2022).
Xeroderma pigmentosum complementation group C (2 papers, 2019 to 2023). "E-cadherin is proven to promote nucleotide excision repair by increasing the expression of xeroderma pigmentosum complementation group C (XPC) and DNA damage-binding protein 1 (DDB1) in the event of ultraviolet-induced DNA damage." (PMID 31547193, 2019). "Such proteins are tDNA damage-binding protein 1 (DDB1), ERCC2, Xeroderma pigmentosum complementation group A (XPA), and xeroderma pigmentosum complementation group C (XPC)." (PMID 37206523, 2023).
atherosclerosis (1 paper, 2026). A disease characterized by the build-up of fatty material and calcium deposition in the arterial wall resulting in partial or complete occlusion of the arterial lumen. "Our data further demonstrate that, in response to atherosclerosis-related stimuli, CUL4A, DDB1, and CRBN undergo marked cytoplasmic translocation in endothelial cells, leading to increased formation of cytoplasmic CRL4ACRBN complexes." (PMID 41424849, 2026).
bladder cancer (1 paper, 2025). "Both analyses identified DDB1 as an independent prognostic factor for bladder cancer, with hazard ratios of 1.009 (95% CI 1.005–1.014) and 1.0082 (95% CI 1.0034–1.0131), respectively, indicating statistical significance." (PMID 40524221, 2025). "Further multivariate Cox regression confirmed that HIF3A, DDB1, COPS2, and UBE2D3 may independently indicate bladder cancer prognosis." (PMID 40524221, 2025).
congenital hypothyroidism (1 paper, 2025). A thyroid hormone deficiency present from birth. "APP, DDB1, MRPS5, and MRPL33 are hub genes with low expression levels in congenital hypothyroidism (CH)." (PMID 41169358, 2025).
Crohn disease (1 paper, 2012). A gastrointestinal disorder characterized by chronic inflammation involving all layers of the intestinal wall, noncaseating granulomas affecting the intestinal wall and regional lymph nodes, and transmural fibrosis. "Additionally, DDB1- and CUL4-associated factor 7 (DCAF7), the human homolog of SWAN-1, is differentially regulated in the intestinal epithelium and in blood from patients suffering from Crohn's disease or ulcerative colitis, two forms of inflammatory bowel disease." (PMID 22792069, 2012).
DNA repair disorders (1 paper, 2024). "In our cohort, unlike previous cases, a novel autosomal recessive inheritance pattern was identified for the DDB1 gene, as it occurs in most other DNA repair disorders." (PMID 40225931, 2024).
follicular adenoma (1 paper, 2024). "Comparative proteomics analysis using a high-performance liquid chromatography-tandem mass spectrometry approach revealed TSPAN30, DDB1, TYMP, VDAC2, and DCXR as the top five candidate biomarkers for directly comparing samples of follicular adenoma and normal thyroid tissue." (PMID 38649381, 2024).
fungal infection (1 paper, 2008). "However, DDB1 does not seem to be required to activate AMP expression induced by fungal infection." (PMID 18833296, 2008).
head and neck squamous cell carcinoma (1 paper, 2025). A squamous cell carcinoma that arises from any of the following anatomic sites: lip and oral cavity, nasal cavity, paranasal sinuses, pharynx, larynx, and salivary glands. "Decreased expression of DDB1 is a risk factor for head and neck squamous cell carcinoma." (PMID 40157540, 2025).
influenza infection (1 paper, 2024). "A global loss of interacting protein partners during influenza infection is observed for both DDB1 and DCAF11, which interact respectively with 69 and 73 proteins only in non-infected cells, and with 19 and 33 exclusively in infected cells." (PMID 39383947, 2024).
Insulin resistance (1 paper, 2022). Increased resistance towards insulin, that is, diminished effectiveness of insulin in reducing blood glucose levels. "Similarly, Ddb1-BKO mice also gained less weight on HFD but developed insulin resistance and partial lipodystrophy, confirming that loss of DDB1 in BAT disrupts whole-body lipid metabolism." (PMID 39872690, 2022). "Instead, both Ddb1-AKO and Ddb1-BKO mice showed decreased body weight on HFD, but they were less healthy because both strains showed decreased glucose clearance rate and developed insulin resistance, resembling a phenotype of partial lipodystrophy." (PMID 39872690, 2022).
microcephaly (1 paper, 2020). A congenital or acquired developmental disorder in which the circumference of the head is smaller than normal for the person's age and sex. "Analogous to the microcephaly-like brains observed in Drosophila ddb1 mutants, in the mouse developing brain, a CNS-specific depletion of DDB1 leads to decreased NSC proliferation and the formation of smaller brains." (PMID 32324743, 2020). "Depletion of ddb1 or mahjong in NSCs leads to delayed NSC reactivation and a microcephaly-like phenotype." (PMID 32324743, 2020).
myelomeningocele (1 paper, 2020). Myelomeningocele is the most severe form of spina bifida. "However, DDB1 has not been previously associated with myelomeningocele." (PMID 32970752, 2020).
neuroendocrine disorder (1 paper, 2026). A disease or disorder that affects the neuroendocrine gland, any of the organized aggregations of cells that function as secretory or excretory organs and that release hormones in response to neural stimuli. "Woodhouse-Sakati syndrome (WSS) is a rare autosomal recessive neuroendocrine disorder caused by pathogenic variants in the DDB1- and CUL4-associated factor 17 (DCAF17) gene." (PMID 42255876, 2026).
pancreatic adenocarcinoma (1 paper, 2019). "However, little is known about the function of DDB1 in pancreatic adenocarcinoma (PDAC)." (PMID 31842285, 2019).
partial lipodystrophy (1 paper, 2022). Loss and redistribution of subcutaneous and/or visceral adipose tissue from specific regions of the body. "The Ddb1-AKO mice showed higher plasma levels of insulin and free fatty acids and significantly elevated liver triglyceride content, resembling the phenotype of partial lipodystrophy." (PMID 39872690, 2022).